INS (insulin)
Diseases named in the same sentence as INS in open-access papers (continued):
Sharing a sentence is not in itself a finding about the gene and the disease.
Insulin resistance (continued). "In essence, the key factors linking peripheral insulin resistance states to cognitive impairment with neurodegeneration and brain insulin resistance, are the increased generation of ceramides in liver, and increased levels of ceramide in peripheral blood." (PMID 22329651, 2012). "There is data to suggest that reduced levels of nitric oxide (NO) within the vascular endothelium contributes to impaired insulin utilization in patients with insulin resistance." (PMID 23028874, 2012). "Plasma fasting glucose, insulin, homeostasis model assessment insulin resistance (HOMA-IR), 25-hydroxyvitamin D, parathyroid hormone and androgen levels were measured before and after treatment." (PMID 25246913, 2012). "Chemerin displays potent anti-inflammatory and insulin-resistance properties, while monocyte chemotactic protein-1—increased in sepsis—contributes to macrophage infiltration in adipose tissue and insulin resistance." (PMID 22272381, 2012). "In the state of chronically increased nutrient load, obesity, and insulin resistance, pancreatic beta cells increase insulin secretion by expanding beta-cell mass." (PMID 22412882, 2012). "In rats a high-saturated fat diet is used as a diabetogenic factor increasing insulin and lipid levels and it has been shown to induce severe insulin resistance in skeletal muscles." (PMID 22754464, 2012). "Insulin resistance is defined as an inability to properly respond to either endogenously produced or exogenously administered insulin in peripheral tissues, such as adipose, liver and skeletal muscle tissues." (PMID 22851965, 2012). "Insulin resistance is characterized by a decrease in insulin signaling mainly in the Insulin Receptor Substrate (IRS)/PI-3-kinase/PKB axis that is responsible for most of the metabolic actions of the hormone." (PMID 23316186, 2012). "The ability of C57BL/6 mice to adapt to insulin resistance by increasing insulin secretion is similar to the adaptation to insulin resistance seen in humans." (PMID 23201760, 2012). "A key role in the pathogenesis of GDM is ascribed to insulin resistance increasing during pregnancy, followed by inadequate insulin secretion, in a similar fashion as observed in type 2 diabetes (DM2)." (PMID 22927833, 2012). "Normal beta cells can compensate for insulin resistance by increasing insulin secretion and/or beta-cell mass, but insufficient compensation leads to the onset of glucose intolerance." (PMID 23197974, 2012). "In our work, we tried to determine which factor is more important in the development of DM2 in women with a history of GDM—insulin resistance or defective insulin secretion." (PMID 22927833, 2012). "The homeostatic model assessment (HOMA-insulin resistance) was calculated from the formula (insulin [μIU/mL] × glucose [mmol/L]/22.5) and was 1.51." (PMID 22902344, 2012). "Type 2 diabetes (T2D) is characterized by the inability of beta-cells to secrete enough insulin to maintain glucose homeostasis, usually accompanied by insulin resistance: impaired action of insulin on target tissues." (PMID 22808281, 2012). "Blood Glucose, insulin, leptin, lipid content and fasting insulin resistance index (FIRI) as well as liver and muscle glycogen and lipid contents were determined." (PMID 24250458, 2012). "For example, while B2−/− mice exhibit normoglycemia, hyperinsulinemia and systemic insulin resistance, B1−/− mice are hypoglycemic, hypoinsulinemic and more tolerant to the systemic effects of insulin." (PMID 23024762, 2012). "Recent evidences demonstrate that adipose tissue inflammation links obesity with insulin resistance and that the insulin-sensitizing effects of TZDs result, in part, from their anti-inflammatory properties." (PMID 22529965, 2012).
Insulin resistance (continued). "Leptin interferes with insulin signalling and in type 2 diabetes plasma leptin levels were found to be correlated with the degree of insulin resistance; therefore, insulin resistance syndrome is accompanied by hyperleptinemia as well as hyperinsulinemia." (PMID 22701480, 2012). "We have previously shown that BPA has a direct effect on pancreatic β-cells potentiating glucose-stimulated insulin secretion, which favors postprandial hyperinsulinemia as well as insulin resistance." (PMID 22470480, 2012). "On the other hand, Akt is also involved in insulin desensitization, and increased Akt has been detected in several models of insulin resistance." (PMID 21618539, 2012). "Given that insulin dependent suppression of plasma A-EA is inversely correlated with liver fat, the higher A-EA in this studies diabetic cohort is consistent with insulin resistance and an increased prevalence of NAFLD." (PMID 23144998, 2012). "A longitudinal study of insulin resistance in American children showed that during puberty, insulin sensitivity decreased by ∼50%, with a compensatory increase in plasma insulin which is independent of the changes in body fat." (PMID 22966228, 2012). "Decreased expression of adiponectin correlates with insulin resistance in mouse models of altered insulin sensitivity." (PMID 23024762, 2012). "Predictably, GLUT4 regulation plays a role in obesity-induced insulin resistance, which is characterized by increases in blood glucose and plasma insulin." (PMID 27335671, 2012). "An index of insulin resistance (IR) can be defined as a quantitative measurement of the biological effect of endogenous or exogenous insulin in relation to the ambient blood glucose level." (PMID 22112229, 2011). "In the present study we have examined how a single dietary BCAA, leucine, alters metabolism and insulin signaling in a mouse model of insulin resistance and metabolic syndrome, namely HFD-induced obesity." (PMID 21731668, 2011). "We added the evidence that in a large sample size that serum fetuin-A was associated with insulin resistance indicated as elevated HOMA-IR index and fasting serum insulin levels." (PMID 21556362, 2011). "In GrOW, Hap6 (Frequency-2.6%) was associated with higher insulin levels (p < 0.0001), estimates of HOMA-Insulin Resistance (p < 0.0001) and HOMA-β-cell (p < 0.0001) compared to the common haplotype Hap1 (Frequency-33.2%)." (PMID 20227263, 2011). "The observation group included 61 people with metabolic syndrome (30 patients with MS and normal levels of insulin, 31 people with MS and insulin resistance - IR)." (PMID 21595891, 2011). "This study was undertaken to examine the roles of eNOS in CYP2J3 gene delivery reducing blood pressure and improving insulin resistance in fructose-induced insulin resistant rats." (PMID 22189162, 2011). "Although such alterations are strongly clinically linked to insulin-resistance and metabolic syndrome, the precise opposite findings are seen in the RLIP76−/− mice: insulin-sensitivity, hypoglycemia, hypolipidemia and fat-loss." (PMID 21931813, 2011). "Fasting glucose and insulin were used to calculate the homeostasis model insulin resistance index (HOMA-IR)." (PMID 21736747, 2011). "Hyperinsulinemia associated with insulin resistance reduces insulin transport across the blood brain barrier, BBB, and subsequently lowers insulin levels and activity in the brain." (PMID 21568932, 2011). "Insulin-suppressed EGP reflecting hepatic insulin resistance was greater in T2D and CONm (0.23±0.05; 0.22±0.09; −0.14±0.09 mg.kg−1.min−1, p<0.05 both vs. CONy)." (PMID 21779337, 2011). "In the case of insulin, the increase is generally assumed to be a secondary consequence of obesity and insulin resistance." (PMID 22180729, 2011).
Insulin resistance (continued). "Inflammatory cytokines such as TNF, IL-6 and MCP-1 have been also shown to inhibit insulin action through modification of signaling properties of insulin receptor substrates, contributing to liver and skeletal muscle insulin resistance." (PMID 21789167, 2011). "The risk of cancer-related mortality is increased in those with high insulin levels or insulin resistance and cancers of the breast, prostate and colorectum." (PMID 21696633, 2011). "Compared to values in the normal group, serum insulin, insulin resistance (HOMA-IR) and serum triglycerides were all higher, while urine osmolarity was lower in fructose-treated rats (all P < 0.05)." (PMID 22189162, 2011). "Cardiac uptake and utilization of glucose is nevertheless inhibited during beta-blocker intoxication due to hypoinsulinaemia and acquired insulin resistance, effects reversed in the presence of insulin." (PMID 21541209, 2011). "The novel finding that insulin stimulates PDE-5 expression can explain the reduced response to sildenafil therapy in diabetic patients with elevated insulin resistance and hyperinsulinemia." (PMID 21297971, 2011). "When reduction in insulin function (insulin resistance) occurs, euglycemia is maintained by increased insulin secretion (hyperinsulinemia)." (PMID 21829658, 2011). "Some studies also showed the relationship between hypertension and cholesterol, glucose, insulin, and insulin resistance." (PMID 22187624, 2011). "Insulin resistance is defined as impaired sensitivity to insulin in its main target organs (muscle, liver and adipose tissues), and is considered a hallmark of type 2 diabetes." (PMID 21738773, 2011). "The MetS-BMI interaction was significant for fasting glucose, 2-hour plasma glucose, fasting plasma insulin and insulin resistance (HOMA-IR)(p < 0.001 for all)." (PMID 21962038, 2011). "During stress, the generation of elevated amounts of TNF-α impairs insulin signaling, leading ultimately to insulin resistance." (PMID 19884114, 2011). "We have shown for the first time that offspring born following this procedure had increased adiposity, increased plasma insulin, impaired glucose tolerance and glucose stimulated insulin secretion and increased whole body insulin resistance." (PMID 21494686, 2011). "Accordingly, Sirt1 activators improve insulin resistance in ob/ob and diet-induced obese mice, and increase insulin sensitivity in obese, insulin-resistant Zucker rats." (PMID 21426570, 2011). "In a model of high-fat diet-induced insulin resistance in rat, the administration of T2, on the gastrocnemius muscle, induced remarkable changes on the metabolic/structural phenotype and insulin signaling." (PMID 21941681, 2011). "It is known that due to insulin resistance, ADT causes high insulin levels at equal blood glucose level." (PMID 22110984, 2011). "Among the existing insulin resistance indexes, quantitative insulin sensitivity check index (QUICKI) had the stongest correlation (P = 3.71 × 10-25) with the adiponectin-resistin (AR) index." (PMID 21251282, 2011). "In fact, in subjects who gained weight during the study, insulin resistance increased suggesting that changes in insulin sensitivity induced by CPAP in this setting are mainly determined by changes in body weight." (PMID 21676224, 2011). "These fatty acids and their metabolites inhibit insulin-stimulated glucose transport, subsequently leading to insulin resistance." (PMID 21379380, 2011). "NAFLD has a close association with disordered insulin utilization in the body, thus patients with NAFLD often suffer from insulin resistance and Type II diabetes." (PMID 21645344, 2011). "Let us now briefly review the molecular mechanisms by which insulin and hyperinsulinemia, particularly when it occurs in the setting of insulin resistance, can augment proliferative events." (PMID 21668983, 2011).
Insulin resistance (continued). "First studies testing TUDCA in obese subjects with insulin resistance have also resulted in promising results, an increase in hepatic and muscle insulin sensitivity." (PMID 21568932, 2011). "Since the insulin resistance is selective and only restricted to the effect of insulin on glucose transport, the high insulin levels can still act on the osteoblast to increase BMD." (PMID 21772974, 2011). "The core pathophysiology of type 2 diabetes (T2DM) has been attributed to the classic triad of decreased insulin secretion, increased insulin resistance, and elevated hepatic glucose production." (PMID 22174491, 2011). "In the context of the rising incidence of insulin resistance, obesity, and cancer more attention has become focused on improving glycemic control, specifically insulin responsiveness, through altering dietary macronutrient ratios." (PMID 21375752, 2011). "Stimulatory effect of hyperinsulinemia on farnesyltransferase in the presence of insulin resistance represents one potential mechanism responsible for mitogenicity and atherogenicity of insulin." (PMID 21668983, 2011). "Overexpression of HO-1 activates the insulin-signaling pathway and has been shown to have unique and long-lasting antidiabetic effects in the rodent model of insulin resistance." (PMID 22220267, 2011). "In mice that consumed HFD and received only 1 injection of STZ it is clear, judging from the data, that glucose tolerance is maintained in these animals by their ability to secrete sufficient quantities of insulin to compensate for impaired insulin resistance." (PMID 22164157, 2011). "This correlated with echocardiographicevidence of diastolic dysfunction (considered asan early marker of CAD), plasma insulin and uricacid; thus linking hyper homocysteinemia withthe insulin resistance of PCOS." (PMID 24963365, 2011). "This suggested that this peptide played an important role in the insulin-IGF cross talk and was thus closely linked to insulin resistance." (PMID 22242132, 2011). "The involvement of muscle triacylglycerol (TAG) storage in the onset of insulin resistance is questioned and the attention has shifted towards inhibition of insulin signalling by the lipid intermediate diacylglycerol (DAG)." (PMID 21264296, 2011). "Inflammation plays a major role in obesity-induced insulin resistance by the release of multiple inflammatory cytokines that oppose insulin signaling." (PMID 21356117, 2011). "This study bolsters our former finding of positive association between anti-human PDI and insulin resistance, an association we postulated to be due to the inhibition of PDI mediated insulin degradation." (PMID 21949836, 2011). "TZDs are insulin sensitising drugs that reduce peripheral insulin resistance and blood glucose levels." (PMID 21347323, 2011). "HOMA-AD is a modified version of homeostasis model assessment of insulin resistance (HOMA-IR) index which calculated from the product of serum insulin and plasma glucose levels divided by serum adiponectin levels." (PMID 21251282, 2011). "Acquired by stratified analysis, the higher the BMI, the higher level of insulin and homeostasis model assessment for insulin resistance (HOMA-IR) (P < 0.01) were found in HCC patients." (PMID 21569630, 2011). "The trigger is then the destruction of pancreatic β cells, leading to an inability for residual islets to secrete adequate amounts of insulin to compensate for insulin resistance." (PMID 22164157, 2011). "Insulin sensitivity was assessed by the homeostasis model assessment of insulin resistance (HOMA-IR)." (PMID 21303562, 2011). "Recently, we found an association between post-streptococcal autoantibodies against Protein Disulphide Isomerase (PDI), an enzyme involved in insulin degradation and insulin resistance." (PMID 21949836, 2011). "The data on the relationship between hypertension and lipid profiles, glucose, insulin, and insulin resistance among Chinese children were limited." (PMID 22187624, 2011).
Insulin resistance (continued). "At the nexus of obesity-related co-morbidities is insulin resistance, which is characterized by a reduced responsiveness of insulin-sensitive tissues such as skeletal muscle, adipose tissue and liver to insulin-mediated glucose and lipid metabolism." (PMID 22194858, 2011). "We found that young patients with PCOS had higher levels of MS inclusion criteria such as serum TG, TC, LDL, FBS, insulin, insulin resistance (HOMA-IR) and lower levels of serum HDL." (PMID 22024243, 2011). "The model utilize a set of empirically derived nonlinear equations to predict the homeostatic concentrations of fasting insulin and glucose, which reflect the varying degrees of pancreatic β-cell function and insulin resistance." (PMID 22004541, 2011). "On the other hand, the administration of recombinant human vaspin improved insulin sensitivity and glucose tolerance, and reverses the expression of those genes that can promote insulin resistance such as leptin, resistin and TNF-α, in diet-induced obese mice." (PMID 21526992, 2011). "Insulin resistance is defined as the decreased responsiveness of target tissues to ordinary levels of insulin and plays a central role in the development of metabolic disorders such as type 2 diabetes, hypertension, and dyslipidemia." (PMID 21464990, 2011). "The insulin resistance was evaluated by HOMA-IR index or serum insulin levels, instead of the hyperinsulinemic-euglycemic clamp." (PMID 21556362, 2011). "Adiponectin is thought to have novel insulin-sensitizing property in vitro and in vivo, and suggested that it plays a protective role against insulin resistance." (PMID 20008903, 2011). "Hyperglycaemia, characterised by high fasting glucose and insulin levels, and impaired β-cell function are markers of insulin resistance." (PMID 21915122, 2011). "Insulin resistance, which can be defined as a state of reduced responsiveness to normal physiological levels of insulin regarding both glucose and fatty acid utilization, plays a major role in the development of type 2 diabetes mellitus (T2DM)." (PMID 21760887, 2011). "In conclusion, we propose that β-cells in patients with T2DM are able to enter the cell-cycle, but fail to proliferate successfully to compensate for peripheral insulin resistance due to dysfunctional insulin signaling and cell-cycle arrest." (PMID 22140505, 2011). "In our study, fasting insulin levels and postprandial insulin levels decreased following intervention, while indexes of insulin resistance improved." (PMID 21603203, 2011). "We chose HOMA, fasting insulin levels, and peak insulin levels as measures for insulin resistance, since these parameters have been used in comparable studies performed in children and adolescents." (PMID 21904547, 2011). "TLR4 mutant mice compared to WT mice had significantly higher fasting blood glucose, serum insulin, insulin resistance, serum leptin, and serum cholesterol when they received TF diet (P < 0.05)." (PMID 21314942, 2011). "Particularly, insulin seems to inhibit resistin secretion, while resistin induces insulin resistance, in an insulin-resistin-insulin sensitivity positive feedback loop." (PMID 21760816, 2011). "Taken together, these findings strongly support the in vivo relationship between insulin resistance and ability of insulin to stimulate FTase activity." (PMID 21668983, 2011). "One such familiar consequence of the use of corticosteroids is hyperglycemia as a result of insulin resistance occurring from the reduction of insulin-mediated glucose uptake and utilization." (PMID 22013505, 2011). "Following euglycemic-hyperinsulinemic clamp, we found that DEF mice exhibited hepatic insulin resistance as shown by the higher hepatic glucose production upon insulin stimulation when compared to CT mice." (PMID 21853118, 2011).